AHNAK (AHNAK nucleoprotein)
Diseases named in the same sentence as AHNAK in open-access papers (continued):
Sharing a sentence is not in itself a finding about the gene and the disease.
SARS-CoV infection (1 paper, 2023). "However, some genes were downregulated during SARS-CoV infection, including those for inflammatory cytokines like CXCL8, and genes involved in immune responses such as AHNAK." (PMID 38681774, 2023).
thymoma (1 paper, 2016). A neoplasm arising from the epithelial cells of the thymus. "Desmoyokin, a protein encoded by the AHNAK (neuroblast differentiation-associated) gene, was a protein of interest exhibiting a log2 fold change of -1.81 (q-value 0.0668) in B3 thymomas in relation to A thymomas with known associations with cancer." (PMID 27832160, 2016). "Most notably, desmoyokin, a protein that is encoded by the AHNAK gene, was associated with type A thymomas and medulla of normal thymus, by LC-MS/MS and immunohistochemistry." (PMID 27832160, 2016).
thyroid cancer (1 paper, 2023). "Compared with AHNAK, AHNAK2 in thyroid cancer has been relatively well studied and been considered to influence thyroid cancer progression as a pro-carcinogenic factor." (PMID 38033502, 2023).
tumor (77 papers, 2013 to 2025). "USH2A is frequently mutated in tongue squamous cancer, and AHNAK is associated with tumor metastasis." (PMID 35993362, 2022). "AHNAK previously has been implicated in both pro-tumorigenic and anti-tumor roles of which the most interesting in PitNETs would be its involvement in epithelial-mesenchymal transition." (PMID 36026497, 2022). "The neuroblast differentiation-associated protein AHNAK can promote tumor metastasis by inducing TGFβ-mediated epithelial-mesenchymal transition." (PMID 34905506, 2021). "With the increase of the other factors (risk score and PDGFRA and AHNAK levels), the clinical stage and the tumor stage of patients with BLCA also increased (all p < 0.01)." (PMID 34329197, 2021). "Our data suggest that PANX1 interacts with AHNAK in specialized plasma membrane compartments resembling pseudopodia, which are known to be associated with tumor cell migration and invasion." (PMID 33564071, 2021). "AHNAK (AHNAK Nucleoprotein or Desmoyokin) encodes a large 700 kDa protein involved in calcium channel function, actin cytoskeleton organization and tumor metastasis." (PMID 28642487, 2017). "AHNAK (neuroblast differentiation-associated protein), also known as desmoyokin, is essential for tumor cell migration and invasion." (PMID 26352260, 2015). "AHNAK encodes a protein involved in diverse processes such as blood-brain barrier formation, cell structure and migration, cardiac calcium channel regulation, and tumor metastasis." (PMID 37255988, 2023). "We hypothesize that elevated AHNAK levels in the microenvironment would have unfavorable associations with tumor purity." (PMID 35954405, 2022). "LAMA1 and AHNAK has been implicated in tumor metastasis while TSC2 is considered tumor suppressor." (PMID 36026497, 2022). "AHNAK encodes neuroblast differentiation-associated protein, a cadherin-associated actin binding protein implicated in neural cell differentiation, migration, and tumor metastasis." (PMID 35440587, 2022). "AHNAK has been previously identified as a structural scaffold protein, implicated in a range of cancer-related pathways and processed as an ambiguous factor, which might depend on the type of tumor cells." (PMID 36557813, 2022). "Studies haveidentified AHNAK as a novel tumor suppressor that inhibits M2 alternative activationof tumor-promoting macrophages.Colchicine’s binding to AHNAK protein has been confirmed through molecular dockingand SPR experiments." (PMID 39665079, 2024). "DST and AHNAK genes that were significant from the stage III survival analysis have shown tumour suppressive characteristics in both experimental and computational BC studies." (PMID 36765262, 2023). "Nevertheless, another study reported that AHNAK is an indispensable factor in tumor cell migration induced by TGF-β." (PMID 38033502, 2023). "DEG AHNAK has been considered to act as a tumor suppressor that negatively regulates TNBC cell proliferation." (PMID 37953789, 2023). "Lastly, the EHD2, CTIF, FBXO32, PIP5K1C, and AHNAK genes were found to be co-expressed in the adjacent healthy tissue and tumor tissue groups." (PMID 37365287, 2023). "The majority of work with AHNAK2 has been done in oncology, with some convincing evidence of a pro-oncogenic role, in contrast to the contradictory tumour suppressor and oncogenic roles of AHNAK." (PMID 35158796, 2022). "We believe that the purity of the tumor and multiple immune cells that infiltrate tumors (DC cells, B cells, CD4+ T cells, and CD8+ T cells) were associated with AHNAK expression in BC." (PMID 35954405, 2022). "AHNAK is necessary for pseudopod formation, a key step in the epithelial to mesenchymal transition and tumor cell invasion." (PMID 35440587, 2022). "We found that the AHNAK protein expression level in tumor tissues was higher than that in MPC tissues, and the results were confirmed with Western blotting and immunohistochemistry." (PMID 36557813, 2022).
tumor (continued). "In tumor cells, AHNAK mRNA was found to be significantly enriched in the G0 and G1 phases and substantially reduced in S/G2 of the cell cycle." (PMID 36557813, 2022). "Knockdown of AHNAK in PANX1-expressing Rh18 and Rh30 cells abrogated the PANX1-mediated reduction in cell viability, migration, and increase in anoikis, suggesting that PANX1 regulation of RMS tumor malignant properties involves its interaction with AHNAK." (PMID 33564071, 2021). "The contents of AHNAK are decreased in cancers, and AHNAK negatively modulates cell growth, as well as work as a tumor repressor via potentiation of TGFβ signaling." (PMID 34689136, 2021). "Altogether, these results indicate that the PANX1 tumor inhibitory function in RMS involves its interaction with AHNAK." (PMID 33564071, 2021). "Conversely, AHNAK can act as a tumour suppressor gene and mediates the negative regulation of cell growth." (PMID 33828156, 2021). "AHNAK has recently been described as a novel tumor suppressor gene in BC, especially in the TN subtype, acting via different signaling pathways, such as AKT/MAPK or TGFβ." (PMID 30653559, 2019). "The results showed that there were significant differences in the levels of AHNAK in different types of tumours." (PMID 28494797, 2017). "Compared with the control group, the mean size and weight of tumours of the AHNAK-overexpressing group were significantly lower." (PMID 28494797, 2017). "Six types of tumours showed increases and two types of tumours showed both decreases and increases in the expression of AHNAK." (PMID 28494797, 2017). "Taken together, our results suggest that AHNAK acts as a tumor suppressor that negatively regulates TNBC cell proliferation, TNBC xenograft growth and metastasis via different signaling pathways." (PMID 28494797, 2017). "In tumor cells, AHNAK was recently found to be essential for pseudopodia formation and tumoral migration/invasion." (PMID 23409183, 2013). "AHNAK nucleoprotein was reported as pseudopod-specific proteins in different metastatic human tumor cell lines." (PMID 23590835, 2013). "AHNAK, part of the large nucleoprotein family, is involved in multiple physiological and pathological activities, including lipid metabolism, membrane repair, and tumor migration." (PMID 40308776, 2025). "AHNAK is a giant scaffolding protein of approximately 700 kDa and both tumor-promoting and -suppressive roles of AHNAK have been reported, indicating that AHNAK may function in a cancer type- and cell context-specific manner." (PMID 38890620, 2024). "In multiple types of cancers, abnormal expression of AHNAK and AHNAK2 is associated with prognosis, and they play a key regulatory role in tumor progression by activating signaling pathways such as ERK, MAPK, Wnt, and MEK, as well as promoting epithelial-mesenchymal transition." (PMID 38033502, 2023). "The authors speculated that this “paradoxical” phenomenon may be related to epigenetic modifications and multiple protein interactions, indicating a complex role of AHNAK proteins in tumor regulation." (PMID 38033502, 2023). "AHNAK has been reported to be involved in a variety of biological processes, including cell signaling and contacts, regulation of calcium channels, membrane repair and tumor metastasis." (PMID 35958586, 2022). "Consequently, the results of CCK-8 and EdU experiments suggested that there was a relationship between AHNAK expression and tumor cell proliferation." (PMID 35954405, 2022). "The proliferation of the tumor was significantly inhibited by AHNAK knockdown." (PMID 35954405, 2022).
tumor (continued). "AHNAK was also occasionally upregulated in some area of the tumor stroma." (PMID 34202325, 2021). "Besides, our results illustrated that AHNAK overexpression suppressed tumor growth along with migration in vivo and vitro." (PMID 34689136, 2021). "Taken together, the results illustrated that AHNAK might inhibit tumor infiltration and migration by repressing EMT via modulating the Canonical Wnt cascade." (PMID 34689136, 2021). "Some researchers have also discovered that the AHNAK gene is differently expressed in various human malignancies and abnormal expression of AHNAK may be related to the invasion and metastasis of tumour cells." (PMID 33048468, 2020). "Similarly, a recent study showed that the expression of AHNAK was upregulated in tumor samples, while the TSGene 2.0 database deems it as a tumor suppressor gene." (PMID 33273919, 2020). "The gains in BRD4 and AHNAK may have contributed to metastasis formation: BRD4, part of the Bromodomain and Extraterminal (BET) protein family, regulates tumour cell migration and invasion through transcription of AHNAK." (PMID 32392735, 2020). "In addition, tumour cell pseudopod-specific proteins (AHNAK, Septin-9, eIF4E, and S100A11) were identified from the transcriptome/proteome analysis and closely for pseudopod formation, actin cytoskeleton dynamics, and tumour cell migration and invasion." (PMID 30504808, 2018). "Moreover, we identified PI3K/AKT and MAPK/ERK as key signalling pathways involved in the inhibition of tumour cell proliferation mediated by AHNAK." (PMID 28494797, 2017). "The results thus suggest the role of AHNAK as a tumour suppressor in TNBC." (PMID 28494797, 2017). "Results from this study indicate that AHNAK is needed for vesicle production, and that these vesicles might augment tumor progression by mobilizing CAFs." (PMID 27374178, 2016). "AHNAK (AHNAK Nucleoprotein) may play a role in diverse processes such as blood–brain barrier formation, cell structure and migration, cardiac calcium channel regulation, and tumor metastasis." (PMID 41465209, 2025). "The CpG site cg19758958 is located in the promoter region of the gene AHNAK nucleoprotein (AHNAK), which encodes a structural scaffold protein that may be involved in cell structure and migration, blood-brain barrier, tumor metastasis, and cardiac calcium channels." (PMID 38219005, 2024). "In addition, AHNAK may interact with the tumor microenvironment, invasion, and transformation of tumor cells." (PMID 38103068, 2023). "In a different context, AHNAK may have a tumour suppressor role." (PMID 35158796, 2022). "Also, we validated targets like AHNAK, tumor-specific proteins like TPD52L2, TS101." (PMID 32974197, 2020). "Thus, we confirmed the function of AHNAK in suppressing tumour progression." (PMID 28494797, 2017). "Meanwhile, the elevated AHNAK expression in matCAFs appears to cooperate with their ECM-synthesizing function, facilitating tumor growth through secretion of collagen and other components to establish a tumor-supportive stromal structure." (PMID 40908816, 2025). "AHNAK primarily acts as an inhibitory oncogene in BLCA, with significantly reduced expression in tumor individuals." (PMID 40908816, 2025). "Lymphocyte genes in MM samples which were very downregulated compared to those in HC samples included MYH9, RN7SL2, ACTB, AHNAK and FLNA, which play important roles in cell motility, cell structure, cell migration and tumour metastasis." (PMID 37914759, 2023). "The findings showed that AHNAK, POLE2, SHMT2, NR2F1, and TFRC expression in tumor tissues was substantially higher than in normal tissues (P < 0.05)." (PMID 38103068, 2023). "AHNAK can also inhibit EMT and migration of tumor cells by inducing inactivation of TGF-β signaling." (PMID 38033502, 2023).
tumor (continued). "Actin-dependent pseudopodal protrusion and tumour cell migration, known determinants of EMT, were found to be reliant on four proteins; AHNAK, Septin-9, elF4E and S100A11." (PMID 35158796, 2022). "Through the HPA database, we found that three genes (ABCC9, AHNAK, and DIP2C) had low expression in patients with tumours, whereas eight genes (PLOD1, SLC3A2, RUNX2, RAD9A, CHMP4C, DARS2, CLIC3, and POU5F1) were highly expressed." (PMID 36685927, 2022). "Multivariate Cox regression analysis in the TCGA-BLCA dataset revealed that the expression levels of EMP1, RASGRP4, AHNAK, SLC1A6, and PRSS8 in tumor tissues were independent predictors for the unfavorable prognosis of BUC patients." (PMID 34905506, 2021). "The mRNA expression levels of AHNAK, EMP1, RASGRP4, and HSPA1L were significantly down-regulated in BUC tumor tissues compared with normal tissues while SLC1A6 and PRSS8 were significantly up-regulated (P < 0.05)." (PMID 34905506, 2021). "For instance, up-regulation of ADIPOQ, AGTR1, AHNAK, ENDRA, RBP7 and SLIT2 was correlated with larger tumour size and more advanced tumour stage." (PMID 33184436, 2020). "These sites were annotated to genes involved in diverse biological pathways, including neurological development (AHNAK, PGAP3), lymphocytic function (ITGAL), apoptosis (RELT), tumor suppression (ZGPAT), and endothelial-to-mesenchymal transition (PRSS23)." (PMID 32084330, 2020). "AHNAK was bound to MYCN in all conditions, and has been described as a tumour suppressor that can stimulate the growth suppressing functions of the TGF-β pathway." (PMID 28187790, 2017). "Mechanistically, AHNAK may disrupt intracellular lipid homeostasis via PI3K–Akt signaling, compromising membrane stability/function and ultimately modulating tumor cell viability and metastatic potential." (PMID 40908816, 2025). "AHNAK could inhibit the signals of Wnt/β-catenin, ERK and AKT, resulting in the decrease of EMT, migration and invasion of tumor cells." (PMID 38033502, 2023). "One study indicated that SMYD2 can directly methylate AHNAK as well as multiple sites in the CRU region of AHNAK2, which may be involved in regulating cell adhesion, cell signaling, and tumor cell migration and invasion." (PMID 38033502, 2023). "While three genes (AHNAK, ABCC9, and DIP2C) were highly expressed in normal tissues, eight genes (CHMP4C, CLIC3, DARS2, PLOD1, POU5F1, RAD9A, RUNX2, SLC3A2) were highly expressed in tumour tissues." (PMID 36685927, 2022). "Through the HPA database, we found that three genes, namely ABCC9, AHNAK, and DIP2C, had low expression in patients with tumours, and eight other genes—PLOD1, SLC3A2, RUNX2, RAD9A, CHMP4C, DARS2, CLIC3, and POU5F1—were highly expressed in patients with tumours." (PMID 36685927, 2022). "Consistent with previous findings, we found that the expression of AHNAK is low in several TNBC cell lines and that AHNAK might play a tumour suppressive role." (PMID 28494797, 2017). "Indeed, a number of these genes have been identified as candidate tumor suppressor genes including CREBRF, DIXDC1, AHNAK and TNS2." (PMID 28122328, 2017). "The expression of AHNAK was inversely correlated with the tumour status (P = 0.015), lymph node status (P < 0.001), lymph node (LN) infiltration (P < 0.001) and TNM stage (P < 0.001) of TNBC patients." (PMID 28494797, 2017). "Interestingly, our study also demonstrated that highly expressed AHNAK in the tumor microenvironment has a negative relationship with tumor purity, suggesting a potential link between RBPs and immune cell infiltration." (PMID 35954405, 2022). "Eight genes (SLC3A2, DARS2, DIP2C, PLOD1, RUNX2, ABCC9, AHNAK, and CLIC3) may be involved in the malignant transformation of tumours, and three genes (CHMP4C, POU5F1, and RAD9A) may have a protective effect in patients with tumours." (PMID 36685927, 2022).
tumor (continued). "However, a study suggested that AHNAK can act as a tumor suppressor that mediates the negative regulation of cell growth via the modulation of the TGFβ/Smad signaling pathway." (PMID 33456631, 2020). "Furthermore, the correlation analysis indicated a strong negative correlation between RNF38 and AHNAK protein levels in tumor tissues from HCC patients." (PMID 30836988, 2019). "In previous studies, AHNAK has been suggested to be involved in signalling pathways, such as the reorganization of the actin cytoskeleton network, the PI3K–PKB pathway to engage effector proteins, the formation of pseudopodial protrusions, and adaptation events to reprogram tumour cell biology." (PMID 28494797, 2017). "Moreover, in patients with TNBC, the expression of AHNAK gene was inversely correlated with the tumor status (P = 0.015), lymph node status (P < 0.001), lymph node (LN) infiltration (P < 0.001) and TNM stage (P < 0.001)." (PMID 28494797, 2017). "Moreover, AHNAK could, at least partially, affect the AKT/MAPK and the Wnt/β-catenin signalling pathways, which are important tumour-related signalling pathways in TNBC." (PMID 28494797, 2017). "Existing evidence indicates that AHNAK overexpression activates the PI3K–Akt signaling pathway, which serves as a central metabolic regulator and may suppress glycolysis via downstream effectors, thereby reducing glycolytic metabolite production and impairing tumor cell survival and invasiveness." (PMID 40908816, 2025). "ND GBM pre-surgery saliva (NDT0) showed the exclusive characterization of peptide fragments of CDA, HOPX, FABP5, WIPF3, VOPP1, AHNAK, and DAZAP1 proteins, which, to the best of our knowledge, have not been previously identified in relation to GBM tumor." (PMID 41155285, 2025). "AHNAK plays a key role in regulating blood-brain barrier formation, cell structure and migration, cardiac calcium channel signaling, and tumor metastasis, while there is a relative lack of functional research on AHNAK2, a homologue of AHNAK." (PMID 32904605, 2020).